TTF1 (transcription termination factor 1)
Diseases named in the same sentence as TTF1 in open-access papers (continued):
Sharing a sentence is not in itself a finding about the gene and the disease.
nodular goiter (1 paper, 2016). Goiter characterized by discrete tissue mass(es) that may or may not produce thyroid hormones. "The current study showed that low iodine status in nodular goiter was associated with high levels of expression of TTF-1 and PAX8." (PMID 27525008, 2016). "TSHR expression in nodular goiter lesions may be associated with upregulated expression of transcription factors TTF-1 and PAX8." (PMID 27525008, 2016). "Upregulation of TSHR, TTF-1, and PAX8 is associated with low follicular lumen iodine content in nodular goiter." (PMID 27525008, 2016). "Results showed that, in addition to the increase in TSHR expression, nodular goiter lesions also expressed significantly more TTF-1 and PAX8 than normal thyroid tissues." (PMID 27525008, 2016). "in addition to the increase in TSHR expression, the expressions of TTF-1 and PAX8 in nodular goiter lesions were also significantly higher than those in control tissues." (PMID 27525008, 2016). "The Spearman rank coefficient was performed to determine the correlation among the parameters of TSHR, TTF-1, PAX8, and iodine in 30 nodular goiter and control samples." (PMID 27525008, 2016). "Western blot immunohistochemistry was performed to assay TSHR, TTF-1, and PAX8 in thyrocytes of nodular goiter as well as in extranodular normal thyroid tissues." (PMID 27525008, 2016). "Western blot was performed to determine the expression of TSHR, TTF-1, and PAX8 in 10 nodular goiter and 10 control thyroid samples." (PMID 27525008, 2016). "Immunohistochemistry was also performed to determine TSHR, TTF-1, and PAX8 expression in 30 nodular goiter and 30 control thyroid samples." (PMID 27525008, 2016). "TTF-1 and PAX8 were confined to the nucleus of the thyrocytes, and both types of immune reactivity in nodular goiter were significantly higher than those in the control." (PMID 27525008, 2016). "The TSHR, TTF-1, and PAX8 in nodular goiter were significantly higher than those in the controls." (PMID 27525008, 2016).
NUT carcinomas (1 paper, 2022). "Both cases diffusely expressed p63 and NUT consistent with classic NUT carcinoma, but one case also showed patchy cytokeratin 7, Napsin-A, and TTF1 expression in the micropapillary component, consistent with some divergent adenocarcinoma differentiation." (PMID 34997561, 2022).
ovarian mucinous carcinoma (1 paper, 2019). "TTF-1 and Napsin A, which are commonly-used pulmonary-origin markers, are helpful in distinguishing these cases from cases of primary ovarian mucinous carcinoma." (PMID 31455365, 2019).
pancreatic NEN (1 paper, 2025). "Detailed characterization of pulmonary NEC, pulmonary carcinoid, pancreatic NEN, ileal NEN, and MiNEN was performed using immunohistochemical staining to detect pan-cytokeratin (panCK), Thyreoglobulin (TG), Calcitonin (CT) and the transcription factors CDX2, SATB2, TTF1, GATA3, ARX and PDX1." (PMID 41145514, 2025).
paranasal sinus tumors (1 paper, 2025). "Among the seven reported cases of metastatic paranasal sinus tumors with available immunostaining results, six cases of DTC were positive for thyroglobulin or TTF-1, while one case of MTC exhibited positive staining for calcitonin and TTF-1." (PMID 40391014, 2025).
pneumonitis (1 paper, 2013). An inflammatory process affecting the lung parenchyma. "DS1-treated dogs also had less pneumonitis, detected by CT scan imaging, and significantly more TTF1+ cells detected by IHC, in the bronchioles and alveoli compared to control dogs." (PMID 23520463, 2013). "The DS1-treated dogs also had less pneumonitis detected by CT imaging and an increased number of TTF-1 (thyroid transcription factor 1, NKX2-1) positive cells in the bronchioli and alveoli compared to control dogs." (PMID 23520463, 2013).
primitive neuroectodermal tumor (1 paper, 2021). A malignant neoplasm that originates in the neuroectoderm.
pulmonary fibrosis (1 paper, 2017). Chronic progressive interstitial lung disorder characterized by the replacement of the lung tissue by connective tissue, leading to progressive dyspnea, respiratory failure, or right heart failure. "Mutations in the gene encoding TTF-1, NKX2-1, have been associated with development of ILD and pulmonary fibrosis." (PMID 29085824, 2017).
pulmonary hamartomas (1 paper, 2025). "Markers such as Napsin A and TTF‐1, typically indicative of pulmonary adenocarcinoma, may show positivity due to the presence of entrapped benign respiratory epithelium within pulmonary hamartomas, rather than true malignant expression." (PMID 41415017, 2025).
renal dysfunction (1 paper, 2022). "On the other hand, it could be assumed that patients who were TTF-1-negative were resistant to numerous cytotoxic chemotherapeutic agents and may not benefit from the use of PEM when even patients with nonsq NSCLC have resulting interstitial pneumonia or renal dysfunction." (PMID 36614938, 2022).
respiratory failure (1 paper, 2011). The significant impairment of gas exchange within the lungs resulting in hypoxia, hypercarbia, or both, to the extent that organ tissue perfusion is severely compromised. "We report a novel TTF-1 molecular defect causing recurrent respiratory failure episodes in an infant." (PMID 21867529, 2011).
sebaceous carcinoma (1 paper, 2022). "The primary lesion was incompletely excised in another hospital, and a histopathological exam showed sebaceous carcinoma G3 (immunohistochemical profile: CKAE1/AE3 (+), CK7(+), CK20(−), D2-40(−), TTF1(−), p40(−), S100(−))." (PMID 35205753, 2022).
sinonasal carcinomas (1 paper, 2025). "Caution should be exercised when interpreting the expression of lineage-specific markers, such as TTF1 and CDX2, in poorly differentiated sinonasal carcinomas to avoid misclassification." (PMID 40366517, 2025).
skin tumors (1 paper, 2007). "With the exception of cases with skin tumors, TTF-1 could not be reliably used to distinguish primary from metastatic SmCC in extra-pulmonary sites." (PMID 17803816, 2007).
T-cell lymphoma (1 paper, 2024). "TTF-1 positivity in thymoma, T-cell lymphoma, and large cell B-cell lymphoma may also cause diagnostic confusion if seen in thoracic or lympho-nodal tumor masses." (PMID 39377914, 2024).
thyroid angiosarcomas (1 paper, 2024). "By immunohistochemistry, thyroid angiosarcomas are strongly and diffusely positive for pan-endothelial markers, i.e., CD31, CD34, FLI-1 and ERG, but lack expression of thyroid-related immunomarkers including thyroglobulin, TTF1 and PAX8." (PMID 39422760, 2024).
thyroid autoimmune diseases (1 paper, 2021). "In addition, studies have shown that TTF-1 may lead to the occurrence of thyroid autoimmune diseases by regulating the expression of MHC-I molecules." (PMID 34631891, 2021).
urothelial carcinoma (1 paper, 2024). A malignant neoplasm derived from the transitional epithelium of the urinary tract (urinary bladder, ureter, urethra, or renal pelvis). "The suboptimal specificity is due to small but significant fractions of TTF-1 positive cases in many common tumor entities such as adenocarcinomas of the colorectum, stomach, pancreas, prostate, ovary, and uterus, as well as urothelial carcinomas." (PMID 39377914, 2024).
uterine tumors (1 paper, 2023). "However, no TTF1-positive cells were detected within the lung nodules or in the uterine tumors." (PMID 36906706, 2023).
vaginal carcinosarcoma (1 paper, 2025). An aggressive mixed epithelial and mesenchymal neoplasm that arises from the vagina and is characterized by the presence of a malignant epithelial component and a malignant mesenchymal component. "Our initial diagnosis was primary vaginal carcinosarcoma; however, additional immunohistochemistry of the tumor revealed luminal membranous positivity for CD10, diffuse nuclear staining for TTF1, and estrogen receptor negativity." (PMID 40851723, 2025).
tumor (533 papers, 2005 to 2026). "Future research should aim to explore the biological mechanisms underlying the relationship between TTF-1 expression and tumor behavior, especially in the context of brain metastases." (PMID 39630375, 2025). "Univariate analysis did not reveal a statistically significant association between mDFS and age, gender, smoking history, tumor localization, TTF-1, chromogranin A, synaptophysin, CD56, adjuvant radiotherapy, or type of surgery." (PMID 41153253, 2025). "Immunohistochemical markers such as CK-7, Glypican 3, and TTF-1 showed significant diagnostic value between tumor subtypes." (PMID 40804826, 2025). "In the exosome cohort CXCL12 expression was strongly correlated with EGFR status, CD44v6 was associated with tumor stage, TTF-1 expression & chromogranin protein expression and HIF1A & TGFBR2 showed positive correlation with CEA expression & CK20 expression." (PMID 38877052, 2024). "Ultimately, the results obtained highlighted that the gradual loss of mutual exclusivity between TTF1 and p40 was correlated with an equally progressive worsening of the prognosis and a greater risk of recurrence, irrespectively of the tumor subtype." (PMID 38291083, 2024). "Our results showed that TTF1 and NapsinA expression were associated with the female sex and smaller tumor sizes." (PMID 32876329, 2021). "In PTC, reduced nuclear localization of TTF-1 is linked to vascular invasion and nodal metastases and is a strong predictor of tumor recurrence in the presence of BRAF mutation." (PMID 33578751, 2021). "In cases with combined adenocarcinoma-large cell undifferentiated carcinoma in the primary tumor, the metastasis was composed exclusively of the undifferentiated large cell component which has lost the TTF1 reactivity with variable loss of pancytokeratin." (PMID 33506327, 2021). "Targeting of Stk11 also led to the establishment of KRT5+/TTF1– tumors, indicating that loss of this tumor suppressor leads to the simultaneous development of NSCLC-SCC and NSCLC-ADC." (PMID 33738287, 2021). "In conclusion, our results revealed a significant association of PD-L1 expression with female sex, central tumor location, TTF-1 expression, and prognosis of the patients with SCLC." (PMID 33585516, 2020). "Multivariate Cox regression revealed that mutation type, tumor stage, and thyroid transcription factor-1 (TTF-1) expression status were the main factors influencing patient prognosis." (PMID 31380265, 2019). "These NSCLCs express proteins such as cytokeratin-7 (CK7) and thyroid transcription factor-1 (TTF1) which are diagnostic markers of the tumor." (PMID 29415661, 2018). "In this study, tumor differentiation was associated with TTF-1 expression and resulted in different surgical outcomes." (PMID 29079814, 2017). "TTF-1/HMGA2 axis was associated with tumor differentiation and mediated the aggressiveness of the tumor and prognosis." (PMID 29079814, 2017). "Univariate and multivariate regression analysis revealed that high expression of Orai3 was significantly associated with tumour necrosis, tobacco use, TTF1 expression, and visceral pleural invasion (OR: 5.03) and ERα expression (OR: 5.29) respectively." (PMID 27835593, 2016). "This concept is consistent with the loss of CD56 and TTF-1 expression in PTCs, associated with increased tumor invasiveness in vivo." (PMID 21364949, 2011). "Multivariate analysis demonstrated an independent lower risk of death for patients whose tumour expresses positive TTF1 staining (HR=0.51, 95% CI 0.30–0.85; P=0.01) and higher grade of differentiation (HR=0.40, 95% CI 0.24–0.68; P=0.001)." (PMID 16052216, 2005).
tumor (continued). "Thyroid transcription factor 1 (TTF-1) is frequently used in the immunohistochemical evaluation of LNETs to support a pulmonary origin, yet its diagnostic utility is limited by low sensitivity and heterogeneous expression across tumor subtypes." (PMID 40869558, 2025). "We found that in the tissue cohort CXCL12 expression was strongly correlated with differentiation, CEA & TTF-1 protein expression, CD44v6 was associated with tumor stage and chromogranin protein expression and HIF1A & KRT7 showed positive correlation with CEA expression alone." (PMID 38877052, 2024). "Results showed the correlation between CXCL12 and differentiation grade, CEA and TTF-1 protein expression, CD44v6 was associated with tumor stage, chromogranin expression whereas HIF1A and KRT7 were significantly associated with CEA protein expression in the metastatic tissues." (PMID 38877052, 2024). "The tumor of the palate mucosa was likewise identified as an adenocarcinoma, and the cells showed cytological similarities with the tumor cells in the pleural effusion; TTF-1, Napsin A, EGFR mutation and ALK translocation were all negative." (PMID 30634950, 2019). "These cases suggest the existence of TTF-1-positive and OTP-negative phenotype, which might be related to TTF-1/OTP double-positive biologic group with subsequent loss of OTP due to tumor progression." (PMID 29770932, 2018). "TTF-1/HMGA2 asix is associated with tumor differentiation and aggressiveness." (PMID 29079814, 2017). "Haploinsufficiency of TTF-1 is associated with tumor formation in transgenic mice." (PMID 29079814, 2017). "Indeed, the requirement for malignant cells limits the diagnostic sensitivity and clinical significance of TTF-1, and distinguishes it from assays based on circulating tumor DNA or classical tumor markers." (PMID 26806377, 2016). "There is an ongoing debate on whether the expression of immunomarkers, e.g., TTF1 on tumor cells could help to predict the EGFR mutations in AC patients." (PMID 25086987, 2015). "Napsin A, TTF-1, ERα, and PR were remarkably associated with tumor differentiation." (PMID 24667263, 2014). "In our study, the tumor-associated genes survivin and hTERT, epithelial-specific gene CK-7 and lung or thyroid epithelial-specific TTF-1 were selected, and the positive detection rate of the four gene mRNAs ranged between 35.29 and 61.76%, which is similar to previous studies." (PMID 23599802, 2013). "In addition to TTF-1, various tumor-associated markers were tested." (PMID 36499466, 2022). "Importantly, the poor sensitivity of TTF1 in primary ADC seemed to be linked to tumour grade." (PMID 30078843, 2018). "Immunohistochemistry (IHC) for TTF1/p40 double stain revealed p40 + /TTF1- in the tumor cells and p40-/TTF1 + in the pre-existing epithelial cells." (PMID 42026154, 2026). "We identified a TTF-1/p40-negative tumor cell population with a hybrid adenocarcinoma-squamous expression pattern and upregulation of SLC2A1 (GLUT1)." (PMID 41571939, 2026). "IHC markers showed varying positivity rates across different tumor types, with GATA-3, CDX2, and TTF1 proving particularly useful in distinguishing the tumor origin." (PMID 40751531, 2025). "The next markers found in significant amounts on tumor cells in our study were as follows: TTF-1, cytokeratin, Ki67, and CD56." (PMID 39941799, 2025). "These tumours frequently show expression of TTF-1 (a transcription factor most often detected in tissues of pulmonary or thyroidal origin), absence of GFAP expression and propensity for leptomeningeal spread." (PMID 39899075, 2025). "The tumor expresses TTF-1 and peculiarly estrogen and progesterone receptors but is negative for thyroglobulin and either negative or weakly positive for PAX8, suggesting a lack of definitive follicular cell differentiation." (PMID 40111709, 2025).